HAT1 (histone acetyltransferase 1)
Diseases named in the same sentence as HAT1 in open-access papers (continued):
Sharing a sentence is not in itself a finding about the gene and the disease.
tumor (31 papers, 2019 to 2026). "In esophageal squamous cancer cells, HAT1 inhibition has been shown to cause cell cycle arrest in G2/M, and the use of HAT1 as a therapeutic target in this tumor type is proposed." (PMID 36612223, 2022). "In tumor‐associated Treg cells, Hat1 was found to physically associate with the transcription factor FoxP3." (PMID 31290578, 2019). "In ESC, HAT1 is overexpressed and associated with poor tumor differentiation." (PMID 37048148, 2023). "HAT1 depletion in lung adenocarcinoma and liver cancer, pancreatic cancer, osteosarcoma, and cervical cancer tumor cells causes a decrease in cell proliferation and colony formation and promotes tumor cell apoptosis." (PMID 36612223, 2022). "In BC, HAT1 from the GNAT family induces histone H3 acetylation at the CCR4 promoter in Tregs through the FOXP3/HAT1 complex, promoting Tregs infiltration in the tumor microenvironment and tumor cell immune evasion." (PMID 40313963, 2025). "Both HAT1 and Pan-Kla were elevated in tumor samples compared to normal tissue, and the expression levels of HAT1 and Pan-Kla showed a significant positive correlation." (PMID 41271679, 2025). "We further examined HAT1 in 14 pairs of normal and tumor tissues, and HAT1 was upregulated in the tumor tissues." (PMID 41271679, 2025). "Results showed that tumor volume and tumor weight decreased in the HAT1-KO group as well as the group treated with HAT1 inhibitor." (PMID 41271679, 2025). "HAT1 also functions as a transcription factor to regulate the tumor microenvironment, sensitivity to immunotherapy, and the expression of various genes, such as BCL2L12 and FAS." (PMID 37513949, 2023). "A contradictory role is observed in LC cells, in which the expression of HAT1 is low; however, this seems related to tumor progression." (PMID 37048148, 2023). "In HCC, high levels of HAT1 are correlated with tumor development and are directly related to the tumor stage." (PMID 37048148, 2023). "The specific function of forkhead box P3 (FOXP3)/HAT1 axis is described in BC; it is able to modulate regulatory T-cells (Tregs) infiltration in the tumor microenvironment." (PMID 37048148, 2023). "Specifically, tumors with HAT1 knockdown exhibited the slowest tumor growth, the highest caspase-3 levels, and the lowest Ki67 levels in response to gemcitabine treatment." (PMID 34564701, 2021). "We further detected the IHC staining of HAT1, Ki‐67 and cleaved caspase 3 in tumor samples embedded with paraffin and found that the shHAT1 with ENZ treatment group induced increased apoptosis compared to the other groups." (PMID 34323404, 2021). "Consistently, HAT1 knockdown enhanced the tumor-suppressive effects of gemcitabine in tumor xenografts." (PMID 34564701, 2021). "In both in vitro and in vivo experiments, we demonstrated that the CREB3L2/HAT1/SREBP1 axis promotes tumor cell proliferation and metastasis by enhancing lipid metabolism, and targeting CREB3L2 can partially overcome lenvatinib resistance to augment therapeutic efficacy." (PMID 41285809, 2025). "Subsequently, SUNE1-NC and SUNE1-shHAT1 cells were used to establish xenograft models, and the results showed that knockdown of HAT1 could reduce the tumor growth." (PMID 40050614, 2025). "On the one hand, HAT1 succinylates H3 at K122 to enhance gene expression in tumor cells; on the other hand, it can accelerate its succinylation, increasing its activity and thus tumor formation." (PMID 40865948, 2025). "To further validate the correlation between HAT1 and pan L-lactyllysine (Pan-Kla) expression in clinical samples, we detected global lactylated proteins and HAT1 expression in 14 pairs of normal and tumor tissues from LUAD patients using western blot." (PMID 41271679, 2025). "Therefore, it can be inferred that the succinyltransferase function of HAT1, coupled with the succ of PGAM1 mediated by HAT1, stands as a critical mechanism driving tumor progression." (PMID 39278916, 2024).
tumor (continued). "However, due to the available data, HAT1 has become an attractive target for the rational design of inhibitors that block its activity and induce cell cycle arrest or apoptosis in tumor cells." (PMID 37107673, 2023). "Few scientific observations support a tumor suppressor role for HAT1." (PMID 37048148, 2023). "For example, the discovery of HAT1 inhibitors might be a possible, new way to overcome tumor cells’ immune evasion." (PMID 37048148, 2023). "This may be due to the fact that HAT1 is involved in chromatin assembly and DNA damage repair, and its alterations can induce tumor development, invasion and metastasis." (PMID 34880761, 2021). "We found that HAT1 expression in PCa tissues was higher than that in non‐tumor prostate tissues." (PMID 34323404, 2021). "Furthermore, the knockdown of Hat1 significantly increased tumor infiltration of immune effectors including CD45+CD8+ T cells and CD45+CD4+ T cells, but decreased the infiltration of CD11b+Gr1+ myeloid cells in tumors." (PMID 30709380, 2019). "In agreement with the effect on tumor regression, treatment with the anti-PD-1-antibody after the knockdown of Hat1 led to a further decrease in tumor growth and an increase in CD45+CD8+ and CD45+CD4+ T cell infiltration, but a greater decrease in CD11b+Gr1+ myeloid cells in tumors." (PMID 30709380, 2019). "Targeting HAT1 highlights a novel therapeutic target to overcome immune evasion by tumor cells." (PMID 30709380, 2019). "Similarly, we examined the protein level in PDAC and paired adjacent nontumor pancreatic tissues in our hospital via Western blot analysis and demonstrated that HAT1 was upregulated in PDAC compared to adjacent non-tumor pancreatic tissues." (PMID 30709380, 2019). "Moreover, to investigate the role of HAT1 in the tumor growth of PDAC in vivo, PANC-1 cells infected with control or HAT1-specific shRNAs were injected subcutaneously into the right flank of nude mice for the xenograft assay." (PMID 30709380, 2019). "Finally, two of the three kidney samples examined showed the presence of tumor cells, consistent with our frequent observation of tumors on the kidneys of the Hat1+/− animals that spontaneously died." (PMID 31290578, 2019). "Targeting HAT1 highlights a novel therapeutic approach to overcome immune evasion by tumor cells." (PMID 30709380, 2019). "Hence, HAT1-mediated resistance to chemotherapy is an internal characteristic of tumor cells." (PMID 34564701, 2021). "In evaluating the expression of HAT1 in LUAD patients using GEPIA and CPTAC databases, we found that the level of HAT1 was elevated in tumor samples compared with normal tissues." (PMID 41271679, 2025). "Furthermore, the expression of HAT1 is correlated with the expression of programmed death-ligand 1 (PD-L1), a ligand for the programmed death 1 (PD1) receptor, which induces the apoptosis of T cells and an underlying mechanism of the immune resistance of the tumor cells." (PMID 37107673, 2023). "The connection was firstly validated between chemokine receptor 4 (CCR4), a tumor-specific chemokine receptor, and FOXP3, shedding light on HAT1′s implication in BC." (PMID 37048148, 2023). "In the TCGA database, the expression levels of HAT1 and SLC39A7 in tumor tissues were higher than those in adjacent normal tissues, while the expression level of MYC in tumor tissues was lower than that in adjacent normal tissues." (PMID 37000317, 2023). "The non-negligible influence of acetylation on tumor immunity has also been reported, and many genes belonging to the histone acetyltransferase family or the histone deacetylase family also serve as tumor immunity regulators, such as GCN5, p300, Tip60, HAT1, and HADCs." (PMID 36503492, 2022). "As to how HAT1 regulates AR expression, there are multiple transcriptional factors, such as MYC, EZH2, TRIM24, KLF4, and BRD4, regulate AR transcription by binding to its promoter in tumor cells." (PMID 34323404, 2021).
tumor (continued). "In the absence of HAT1, PGAM1 succinylation and its activity were reduced in tumour cells and re-expression of a mutant that was not permissive to lysine succinylation (PGAM1-K99R) in PGAM1-KO cells, therefore showed reduced tumour cell proliferation." (PMID 38213532, 2023).
infection (6 papers, 2015 to 2025). The state of being infected such as from the introduction of a foreign agent such as serum, vaccine, antigenic substance or organism. "Overexpression and knockout analyses of HAT1, during infection with CMV, demonstrated that the knockout mutants exhibited greater tolerance to infection than did the overexpressing lines." (PMID 37176135, 2023). "Nonetheless, despite increased growth in vivo, removal of Hat1 renders cells unable to kill the host efficiently over 32 days, consistent with a persistent but avirulent invasive infection." (PMID 26473952, 2015). "Nevertheless, we speculate that the Hat1-mediated oxidative stress regulation may relate to host infection conditions, where severe oxidative stress is a major immune defense during phagocytosis of fungal pathogens." (PMID 26473952, 2015). "Compared with the control group, PCV2 infection significantly upregulated the expression levels of HAT1 mRNA and significantly downregulated the expression levels of HDAC1 mRNA in 3D4/2 cells at 8, 12, 24 or 36 h post-infection (p < 0.05 or p < 0.01)." (PMID 35624806, 2022). "Although the majority of mice survived the infection with cells lacking Hat1, mutant cells were not cleared from the kidneys in 4 out of 5 individuals." (PMID 26473952, 2015).
digestive system cancer (1 paper, 2019). A primary or metastatic malignant neoplasm involving any part of the digestive system. "HAT1 plays a critical role in the tumorigenesis of digestive system cancer." (PMID 30709380, 2019).
HAT1 also shares sentences with these, for which no sentence is quoted: breast cancer (3 papers); esophageal cancer (2); esophageal squamous cell carcinoma (2); lymphoma (2); nasopharyngeal carcinoma (2); adenocarcinoma (1); adrenocortical carcinoma (1); anaplastic oligodendroglioma (1); bacteremia (1); bladder tumor (1); cardiovascular diseases (1); cholangiocarcinoma (1); diffuse large B-cell lymphoma (1); endometriosis (1); heroin addicts (1); ischemic stroke (1); myeloma (1); prostate tumor (1); Sepsis (1); squamous carcinoma (1); steatosis (1); Stroke (1).